TRPM2 (transient receptor potential cation channel subfamily M member 2)
Diseases named in the same sentence as TRPM2 in open-access papers (continued):
Sharing a sentence is not in itself a finding about the gene and the disease.
cancer (continued). "Thus, there is increasing evidence which demonstrates that inhibition of TRPM2 provides chemotherapeutic effects in cancer cells, with little or no harmful effects in non-cancerous cells." (PMID 26178079, 2015). "These mechanistic studies will be particularly important in order to determine whether TRPM2 has different roles, not only in cancerous vs. non-cancerous cells, but also among different types of cancers." (PMID 26178079, 2015). "Current data are suggestive, yet not conclusive, that TRPM2 may indeed have different roles in various types of cancers." (PMID 26178079, 2015). "Furthermore, inhibition of TRPM2 with the specific antagonist, 2-APB, decreased cancer cell proliferation by about 60% and saved non-tumoral cells." (PMID 37507867, 2023).
neurodegenerative disease (18 papers, 2011 to 2026). A disorder of the central nervous system characterized by gradual and progressive loss of neural tissue and neurologic function. "Meanwhile, Ca2+ influx through TRPM2 channel has been considered to be closely linked with cell death and neurodegenerative diseases, and the activation of TRPM2 channel is regulated by oxidative stress." (PMID 36627567, 2023). "All of these provide the foundations for TRPM2 channel as a potential biomarker in neurodegenerative diseases." (PMID 36353687, 2022). "The exploration of the mechanism of TRPM2 as a potential biomarker in neurodegenerative diseases also provides a new approach for the prediction, diagnosis, and prognosis of neurodegenerative diseases." (PMID 36353687, 2022). "It is anticipated that SH-SY5Y cells can be useful for better understanding the molecular and signaling mechanisms for ROS-induced TRPM2-mediated neurodegeneration in the pathogenesis of neurodegenerative diseases." (PMID 30625984, 2019). "As shown by recent studies, using SH-SY5Y cells as a human neuronal cell model should help in interrogating TRPM2-dependent signaling mechanisms in neuronal cell death and related neurodegenerative diseases." (PMID 30625984, 2019). "Following the elucidation of the features of the TRPM2 channel in glial cells, it will shed a light on the study of neurodegenerative diseases." (PMID 26942016, 2016). "Accordingly, our results show the importance of continuing studies to determine the pathophysiological roles of GSK-3β and TRPM2 in neurodegenerative diseases." (PMID 22188973, 2011). "However, the respective role of neuronal and immune TRPM2 in the progression of these neurodegenerative diseases remains to be clarified in the future." (PMID 41511359, 2026). "Notably, activity of PARP1—an enzyme that produces ADPR -an endogenous activator of TRPM2 channels- is markedly upregulated in several neurodegenerative diseases, including PD and Alzheimer’s disease." (PMID 39117781, 2024). "They showed that amyloid-beta-induced oxidative stress determines a neurovascular dysfunction through TRPM2 overactivation, suggesting that TRPM2 inhibition could be a therapeutic target for this neurodegenerative disease." (PMID 38390373, 2023). "In this way, TRPM2 channel plays an important part in neurodegenerative diseases." (PMID 36353687, 2022). "By exploring the gating process of TRPM2 channel, our work helps us better understand the mechanism of TRPM2 as a potential biomarker in neurodegenerative diseases, and provides a new approach for the prediction, diagnosis, and prognosis of neurodegenerative diseases." (PMID 36353687, 2022). "Given that TRPM2 is most abundantly expressed in the brain and that FPP-induced acute cell death is dependent on TRPM2 function, we sought to determine whether the FPP/TRPM2 signaling axis contributes to brain cell death in neurodegenerative diseases." (PMID 33901180, 2021). "Recent studies, using TRPM2-knockout mice in combination with disease models, support a critical role for the TRPM2 channel in mediating ROS-induced neuronal death and in contributing to the pathogenesis of ischemia-reperfusion brain damage and neurodegenerative diseases, such as AD." (PMID 30625984, 2019). "Additionally, its ability to respond to ROS has made TRPM2 a potential therapeutic target for chronic inflammation and neurodegenerative diseases." (PMID 29997338, 2018). "Although implicated in oxidative stress-induced neuronal cell death, and potentially in neurodegenerative disease, the physiological role of TRPM2 in the central nervous system is unknown." (PMID 22188973, 2011). "However, there are still many further studies remaining to be performed to elucidate the detailed mechanism of glial TRPM2 channel in the plasticity of CNS and the pathology of neurodegenerative diseases such as AD, particularly using specific deletion of TRPM2 channel in glial cells." (PMID 26942016, 2016).
neurodegenerative disease (continued). "Interestingly, TRPM2 expression is greatest in the central nervous system (CNS) where it may contribute to neurodegenerative disease." (PMID 22188973, 2011). "The transient receptor potential melastatin 2 (TRPM2) is a calcium‐permeable nonselective channel involved in the pathological mechanism of several inflammatory and neurodegenerative diseases." (PMID 40665621, 2025). "Transient receptor potential melastatin 2 (TRPM2), a non-selective cation channel, is involved in many physiological and pathological processes, including temperature sensing, synaptic plasticity regulation, and neurodegenerative diseases." (PMID 36353687, 2022).
infection (15 papers, 2014 to 2026). The state of being infected such as from the introduction of a foreign agent such as serum, vaccine, antigenic substance or organism. "TRPM2 activity is thought to be regulated by physiological body temperature within the circadian fluctuation and hyperthermia caused by infection and inflammation; thus, TRPM2 participates in a wide range of physiological functions." (PMID 39919606, 2025). "Research also revealed that TRPM2-/- mice are highly susceptible to infection with Listeria monocytogenes (Lm); post-infection decreased the levels of interleukin-12 and interferon-γ." (PMID 39007141, 2024). "Using H. pylori as an infection model, the same group showed that the loss of TRPM2 resulted in increased macrophage-mediated inflammatory gastritis and decreased H. pylori colonization compared to WT mice." (PMID 37576339, 2023). "Here, we aimed to elucidate the cellular innate inflammatory mechanisms responsible for the increased susceptibility of Trpm2−/− mice to infection with L. monocytogenes." (PMID 32117251, 2020). "Numerous proinflammatory cytokines are produced during the innate immune response to infection and inflammation, several of which have been linked with activation of TRPM2." (PMID 29997338, 2018). "For example, Knowles and colleagues reported that TRPM2-depleted mice were more susceptible to infection with Listeria monocytogenes (LM) and exhibited lower production of the cytokines IL -12 and IFNγ compared with WT mice, suggesting a role for TRPM2 in combating LM infections." (PMID 37576339, 2023). "As discussed in the context of the infection model, TRPM2 deficiency in cells other than T cells could mask an altered CD4+ T-cells response." (PMID 35095852, 2021). "However, depletion of neutrophils in Trpm2−/− mice, drastically reduced the areas of infection in the liver, suggesting that deficiency of TRPM2 ion channel in neutrophils promotes bacterial dissemination in spleen and liver of mice infected with L monocytogenes." (PMID 32117251, 2020). "In contrast, beneficial functions of TRPM2 in enhancing host defense have been reported in several infection/inflammation models." (PMID 39919606, 2025). "TRPM2-mediated Ca2+ entry controls the ROS-induced chemokines responsible for the recruitment of inflammatory cells to sites of injury or infection." (PMID 38308007, 2024). "In the same Lm model, TRPM2-/- mice presented with septic shock during infection and increased serum levels of TNF-α, IL-6 and IL-10." (PMID 39007141, 2024). "Transient receptor potential cation channel subfamily m member 2-like (TRPM2) was the most down-regulated gene 14 post NNV infection." (PMID 38068937, 2023). "Factors influencing the polarization and subsequent outcome of infection have been identified in various reports, including the expression of the cation channel transient receptor potential melastatin 2 (TRPM2)." (PMID 35886908, 2022). "Here, we analyze the response of CD4+ and CD8+ T cells from Trpm2-/- mice in vitro and in infection and inflammation models in vivo." (PMID 35095852, 2021). "Since Trpm2−/− mice developed systemic inflammation and succumbed at the acute phase of the infection, we first investigated how phagocytic cells contribute to the pathobiology leading to lethality in these mice." (PMID 32117251, 2020). "Similar to the Ccr2−/− group, only 30% of the Trpm2−/− mice survived 5 dpi and by 6 dpi 100% of this group had succumbed to the acute infection." (PMID 32117251, 2020). "Altogether, the multiple key functions of TRPM2 appear to define the dynamic effector response of neutrophils during the onset of infection and/or inflammatory processes." (PMID 32117251, 2020). "Depletion of neutrophils in WT or Trpm2−/− mice also modified the inflammatory liver microenvironment following infection." (PMID 32117251, 2020).
infection (continued). "The deficient production of IL-12 and IFN-γ in the TRPM2−/− mice led to a significantly lower survival rate after Listeria monocytogenes infection, supporting a vital role for the TRPM2 channel in the innate immune response to this infection." (PMID 29997338, 2018). "The production of IL-6 and TNF-α was however enhanced in LPS-treated macrophages from the TRPM2-KO mice and in response to LPS-induced infection in the TRPM2-KO mice." (PMID 26300888, 2015). "Consequently, additional research is required to evaluate the therapeutic potential of manipulating TRPM2 more accurately is innate inflammation and infection." (PMID 37576339, 2023). "In addition to its contribution to innate immunity, TRPM2 has also been shown to play a crucial role in defense against infections." (PMID 37576339, 2023). "However, the study did not address how phagocytes participate in the pathobiology of the infection or the induction of systemic inflammation by L. monocytogenes infection in Trpm2−/− mice." (PMID 32117251, 2020). "Whereas, WT or neutrophil depleted WT mice showed reduced areas of bacterial accumulation, as compared to Trpm2−/− mice, depletion of neutrophils in Trpm2−/− mice resulted in even further reduction in bacterial dissemination in the spleen during the acute infection." (PMID 32117251, 2020). "Interestingly, infected Trpm2−/− mice treated with anti-Ly6G had a reduced bacterial burden at 72 hpi, suggesting that the expression of TRPM2 ion channel in neutrophils impedes bacterial dissemination during the infection with L. monocytogenes." (PMID 32117251, 2020). "Furthermore, three recent studies have examined the role of TRPM2 channels in the CXCL2 production by immune cells in responses to infection and there were significant discrepancies in these studies using different cell preparations and infection stimuli." (PMID 26300888, 2015). "Moreover, extracellular ROS release also has a secondary role in recruiting further neutrophils, through H2O2, to the site of infection by activating neutrophil transient receptor potential cation channel, subfamily M, member 2 (TRPM2), contributing to further intestinal inflammation." (PMID 41252181, 2026). "Thus, TRPM2 deficiency restricted to CD8+ T cells did not significantly impair their response during acute infection." (PMID 35095852, 2021). "The depletion of neutrophils/monocytes in Trpm2−/− did not significantly change the susceptibility of the mice compared to non-depleted Trpm2−/− mice, and those animals did not survive beyond day 5 after infection." (PMID 32117251, 2020). "To determine how TRPM2 channel modulates the innate inflammatory response induced against L. monocytogenes infection, we infected C57BL/6 (WT), Trpm2−/− or Ccr2−/− mice with a sublethal dose of L. monocytogenes (104 CFU) and evaluated the susceptibility of Trpm2−/− mice to infection." (PMID 32117251, 2020). "Given our demonstration of only a single TRPM2 gene in the equine genome, it is biologically plausible that the short isoforms of TRPM2 in the horse might have altered function that could confer some degree of protection against infection and subsequent tissue damage." (PMID 27919223, 2016). "Moreover, several chemokine receptors, including CXCR4, CXCR5, and CXCR7, were not up-regulated in the TRPM2-deficient DCs, and these cells failed to migrate to the site of infection induced by injection of E. coli." (PMID 26300888, 2015). "In vivo, Trpm2-/- and WT CD8+ T cells showed equal specific responses to Listeria monocytogenes after infection of WT and Trpm2-/- mice and after transfer of WT and Trpm2-/- CD8+ T cells into infected recipients." (PMID 35095852, 2021). "Furthermore, WT and Trpm2−/− neutrophils showed similar levels of TNF-α and IL-6 under infection with L. monocytogenes." (PMID 32117251, 2020).
neurological diseases (11 papers, 2012 to 2026). "In this regard, the role of Mg2+ in the neurological diseases associated with mutations in TRPM2 may well be worth re-examining." (PMID 23236422, 2012). "Future experiments will be required to assess whether TRPM2 currents are also enhanced with age in vivo, and/or in models of neurological disease associated with GSH depletion." (PMID 22487454, 2012). "In addition, TRPM2 mutants have been associated with several neurological diseases." (PMID 23236422, 2012). "It is noteworthy that many other factors, especially Ca2+ permeable ion channels, are also involved in these neurological diseases apart from TRPM2." (PMID 41511359, 2026). "As oxidative stress reaction cell receptors, TRPM2 channels can mediate the oxidative stress reaction—which in turn can mediate the occurrence and development of some nervous system diseases." (PMID 33815104, 2021). "Thus, it seems that TRPM2 deletion in either microglia or neurons contributes to an alleviation in the pathology of different neurological diseases." (PMID 40665621, 2025). "TRPM2 channel is known to be widely distributed in the central nervous system, both in neurons and microglia, and microglial TRPM2 channel had been reported in other neurological diseases." (PMID 40672432, 2025). "Others have reported protective effects of TRPM2 deletion in various neurological diseases." (PMID 40665621, 2025). "Finally, we will discuss pathophysiological roles of TRPM2 channels in the brain and neurological diseases." (PMID 32046066, 2020). "TRPM2’s activation by Ca2+ and ADP ribose (ADPR), an NAD+-metabolite produced under oxidative stress and neurodegenerative conditions, suggests a role in neurological disorders." (PMID 31513012, 2019). "By extension, TRPM2 may represent an important target for the development of novel therapeutic agents of benefit in the treatment of these debilitating neurological diseases." (PMID 22487454, 2012). "Transient receptor potential melastatin 2 (TRPM2) is one of the non-selective cationic channels, and the activity of this channel is triggered by ROS production promoted by deleterious cell death mechanisms in several neurological disorders." (PMID 32825703, 2020).
bacterial infections (7 papers, 2013 to 2026). "By contrast, TRPM2-knockout (TRPM2-KO) mice are susceptible to bacterial infection due to impaired inflammatory responses and uncontrolled bacterial growth." (PMID 23935822, 2013). "Another gene, TRPM2, located near another lead SNP (13_207265708), is closely associated with the innate immune system and may contribute to increased susceptibility to bacterial infections, potentially leading to mortality." (PMID 37990155, 2023). "Additionally, in the CLP model or inflammation caused by bacterial infections such as Lm, E. coli, and H. pylori, TRPM2 channel activation was found to suppress the inflammatory response, likely due to enhanced bacterial clearance by macrophages and neutrophils." (PMID 39007141, 2024). "Together, our results suggest an essential functional role for TRPM2 channel in the regulation of neutrophils' inflammatory responses that follow bacterial infection." (PMID 32117251, 2020). "Yet, the mechanisms by which TRPM2 regulates the development of the inflammatory response during bacterial infections are not fully understood." (PMID 32117251, 2020). "At the system level, TRPM2-lacking mice were more susceptible to bacterial infection leading to increased bacterial burden and higher mortality rate." (PMID 41511359, 2026). "However, others reported that TRPM2 is protective and beneficial through combating bacterial infection, exerting anti-inflammatory effect." (PMID 41511359, 2026). "TRPM2 can also suppress inflammatory response induced by bacterial infections." (PMID 39007141, 2024). "It remains unclear whether the anti-inflammatory effects of TRPM2 activation are limited to LPS and bacterial infection-induced inflammation." (PMID 39007141, 2024). "It is, therefore, possible that in addition to neutrophils, macrophages may also contribute to the hyper inflammation observed in the tissue microenvironment upon bacterial infection in Trpm2−/− mice." (PMID 32117251, 2020). "Increasing the intracellular Ca2+ concentration restored the bactericidal activity of macrophages, indicating that TRPM2 regulates the maturation of phagolysosomes in macrophages by controlling intracellular Ca2+ concentration and plays a crucial role in host defense against bacterial infections." (PMID 39007141, 2024). "TRPM2 may play an important protective role during bacterial infections." (PMID 27618067, 2016). "TRPM2 ion channel and its gating molecule ADPR are previously unsuspected players necessary for robust cytokine production and innate cell activation during intracellular bacterial infection." (PMID 29997338, 2018).
cardiovascular disease (5 papers, 2011 to 2024). "We review the roles of TRPM2 in various neurological and cardiovascular diseases as well as in inflammation and the immune system." (PMID 37576339, 2023). "In this review, we examine the structural and biophysical details of TRPM2, its involvement in neurological and cardiovascular diseases, and its role in inflammation and immune system function." (PMID 37576339, 2023). "We also show some future perspectives for the application of TRPM2 inhibitors in cardiovascular system diseases." (PMID 34299254, 2021). "The finding that the TRPM2 channels mediate oxidative stress-induced endothelial hyperpermeability recognises TRPM2 channels as an important factor in vascular barrier dysfunction of cardiovascular disease." (PMID 21291387, 2011).